MTOR (mechanistic target of rapamycin kinase)
Diseases named in the same sentence as MTOR in open-access papers (continued):
Sharing a sentence is not in itself a finding about the gene and the disease.
endometriosis (64 papers, 2015 to 2025). The growth of functional endometrial tissue in anatomic sites outside the uterine body. "The molecular mechanisms underlying autophagy in endometriosis involve the activation of the AMPK/mTOR pathway and the upregulation of autophagy-related genes such as LC3B and Beclin1." (PMID 41209546, 2025). "The road from benign endometriosis to EAOCs is complex, yet most of the implicated cancer driver genes are upstream regulators of the mTOR pathway." (PMID 38893278, 2024). "Activation of the mTOR pathway has also been implicated in the malignant transformation of endometriosis." (PMID 39579091, 2024). "The pathogenesis of endometriosis is complex, involving the activation of the mTOR pathway orchestrated by genetic and epigenetic mutations, which are ultimately implicated in its potential for malignant transformation." (PMID 38893278, 2024). "In this review, we focus on mTOR dysregulation in endometriosis and EAOCs, investigating cancer driver gene mutations and their potential interaction with the mTOR pathway." (PMID 38893278, 2024). "One of the survival pathways implicated in the development and progression of endometriosis and its associated EAOCs is the mechanistic (formerly the mammalian) target of rapamycin (mTOR)." (PMID 38893278, 2024). "We identified two ferroptosis modules of endometriosis, and by enrichment analysis, they are closely linked with autophagy, mTOR, oxidative stress, and FOXO pathways." (PMID 39872538, 2024). "The association between the PI3K/AKT/mTOR pathway and the pathogenesis of endometriosis has been proposed by multiple early studies." (PMID 35408777, 2022). "Other reports have emphasized the role of mTOR signaling in endometriosis-associated carcinogenesis." (PMID 35408777, 2022). "ARID1A mutations, along with PI3K/Akt and mTOR pathway disturbances and epigenetic changes, may contribute to the malignant transformation of endometriosis." (PMID 41465243, 2025). "Compared with endometriosis, stimulants of mTOR and PI3K in healthy mice were associated with the increased activation of primordial follicles, suggesting it as a potential new strategy for in vitro activation of primordial follicles in patients with a poor ovarian reserve." (PMID 38612425, 2024). "Additionally, mTOR signalling has been highlighted in reviews focusing on endometriosis-associated malignancies." (PMID 39579091, 2024). "The PI3K/Akt/mTOR pathway appears to regulate the response of ectopic endometrial tissue to progesterone and is probably associated with progesterone resistance, which is common in endometriosis." (PMID 39579091, 2024). "In fact, the PI3K/AKT/mTOR pathway seems to regulate the response of ectopic endometrial tissue to progesterone and is probably associated with progesterone resistance, which is common in endometriosis." (PMID 35408777, 2022). "Combination therapy of anti-RNA polymerase-1 agents with PI3K/AKT/mTOR inhibitors could be another promising approach to treat endometriosis and the associated malignancies." (PMID 35052864, 2022). "Additionally, some copper metabolism-related genes, such as PDHA1, are downregulated during endometriosis, and mTOR is speculated to regulate copper metabolism in association with PDHA1." (PMID 39579091, 2024). "Therefore, the synergistic action of ARID1A loss and PI3K/AKT/mTOR pathway upregulation in the malignant progression of endometriosis can be partially explained by their cooperation in activating IL-6 and thus in promoting a pro-tumorigenic inflammatory cytokine signaling." (PMID 37627318, 2023). "This metabolic profile suggests a distinct activation state in endometriosis, potentially mediated by mTOR-driven autocrine and paracrine signaling." (PMID 40723209, 2025). "For example, mTOR inhibitors and glycolysis inhibitors can improve the effectiveness of standard treatments by addressing the metabolic dependency of endometriosis lesions." (PMID 40573210, 2025).
endometriosis (continued). "Multiple studies have demonstrated that induced endoplasmic reticulum stress can impede the proliferation and invasion of endometriosis lesions by modulating signaling pathways such as Akt/mTOR, MAPK/ERK, and NF-κB11–15." (PMID 41188339, 2025). "Abnormal endoplasmic reticulum stress response to progesterone enhances the invasiveness of endometrial stromal cells in endometriosis through the AKT/mTOR pathway, which has attracted our interest in the role of endoplasmic reticulum stress in endometriosis." (PMID 41188339, 2025). "Further studies are necessary to validate this pattern and elucidate the potential role of MTOR in mediating the adverse effects of endometriosis on ovarian reserve." (PMID 40002761, 2025). "The activation of the PI3K/AKT/mTOR signaling pathway is significant throughout the transformation from normal endometrium to endometriosis, as revealed by the changed expression of essential pathway components in both eutopic and ectopic endometrium." (PMID 40938862, 2025). "OCCC is frequently linked to endometriosis and characterized by mutations in ARID1A and PIK3CA, hyperactivation of the PI3K/Akt/mTOR pathway, and overexpression of VEGF, HIF-1α, and IL-6." (PMID 41383608, 2025). "A number of studies have shown that the PI3K/AKT/mTOR pathway is deeply involved in the metabolic reprogramming of endometriosis." (PMID 40573210, 2025). "This study aimed to review systematically the current evidence on the efficacy and feasibility of mTOR inhibitors in the treatment of endometriosis, specifically addressing the critical gaps identified in the existing literature." (PMID 39579091, 2024). "We evaluated the potential of mTOR inhibitors as therapeutic agents for endometriosis, examined the secondary benefits related to reproductive function, and assessed how their side effects can be managed." (PMID 39579091, 2024). "Preclinical studies have shown that mTOR inhibitors are effective against endometriosis, even at relatively low concentrations." (PMID 39579091, 2024). "Given that immune dysregulation plays a role in the onset and progression of endometriosis, the clinical use of mTOR inhibitors as immunosuppressive agents presents a compelling opportunity." (PMID 39579091, 2024). "In fact, mTOR inhibitors also showed tumour-reducing effects in a mouse model of endometriosis, and VEGF regulation has been shown to be part of this effect." (PMID 39579091, 2024). "Elevated expression of mTOR and Raptor have been observed in the peritoneal fluid of patients with endometriosis." (PMID 39579091, 2024). "Some reviews have also considered PI3K/Akt/mTOR inhibitors as potential candidates for therapies targeting specific signalling pathways, immunomodulatory approaches, and autophagy in endometriosis." (PMID 39579091, 2024). "Preclinical studies have reported the efficacy of multiple PI3K/Akt/mTOR pathway inhibitors in the treatment of endometriosis." (PMID 39579091, 2024). "Collectively, HIF‐1α and mTOR act as a positive and negative regulator of autophagy, respectively, in endometriosis." (PMID 38645639, 2024). "In studies using human specimens, mRNA analysis of tubal endometriosis samples revealed the activation of the mTOR pathway." (PMID 39579091, 2024). "For example, the efficiency of the mTOR/AKT inhibitor temsirolimus in decreasing endometriotic cell proliferation was confirmed in a mouse model of deep-infiltrating endometriosis." (PMID 38673891, 2024). "The mTOR pathway has been extensively studied as a potential pathway underpinning the initiation and development of endometriosis." (PMID 38893278, 2024). "At least six non-coding RNA molecules related to endometriosis and adenomyosis interact with upstream regulators of the mTOR pathway." (PMID 39579091, 2024). "The impairment of AKT, ERK1/2, and mTOR pathways reduces cell proliferation and survival, further highlighting dienogest’s multifaceted role in managing endometriosis." (PMID 39324359, 2024).
endometriosis (continued). "The therapeutic effects of mTOR and aromatase inhibitors on follicle counts were examined in a rat model of endometriosis." (PMID 39579091, 2024). "A report on the effects of rapamycin, an mTOR inhibitor, in IVF for endometriosis-associated infertility involved 168 women who underwent two IVF cycles." (PMID 39579091, 2024). "When discussing the feasibility of mTOR inhibitors for the treatment of endometriosis, the most critical factor is the control of adverse events." (PMID 39579091, 2024). "Comparison of doses of mTOR inhibitors for endometriosis or endometrial proliferation in in-vivo models with doses for antitumour or immunosuppressive effects." (PMID 39579091, 2024). "Active phosphorylated mTOR expression was found to be 3.5-fold higher in postmenopausal endometriosis compared to premenopausal counterparts." (PMID 38893278, 2024). "Second, the search for and development of novel mTOR modulators with fewer side effects to treat endometriosis remains a challenge." (PMID 38645639, 2024). "This review discusses the mTOR signalling pathway and its role in tumorigenesis, with an emphasis on endometriosis and EAOC." (PMID 38893278, 2024). "We conducted a thorough review of publications on the role of the mTOR pathway and the effectiveness of mTOR inhibitors in endometriosis patients." (PMID 39579091, 2024). "For instance, comprehensive reviews on the signalling pathways involved in endometriosis have discussed the potential role of PI3K/Akt/mTOR." (PMID 39579091, 2024). "Activation of the PI3K/AKT/mTOR signaling cascade is prominent throughout the transformation process from normal endometrium to endometriosis to EAOC, as evidenced by the altered expression of key pathway components both in eutopic and ectopic endometrium." (PMID 37627318, 2023). "Among various signaling pathways that control cell proliferation, PI3K/AKT/mTOR pathway is being studied as a possible component of the pathogenetic mechanism that leads to endometriosis." (PMID 37627318, 2023). "On account of all these findings, PI3K/AKT/mTOR pathway has emerged as an appealing therapeutic target in endometriosis, with scientists attempting to assess the effects of its blockade on the progression of the disease." (PMID 37627318, 2023). "In the same study, subsequent treatment of the mice with the allosteric AKT inhibitor MK-2206 led to a significantly reduced number of formed lesions, thus demonstrating the importance of mTOR signaling in the pathogenesis of endometriosis." (PMID 37627318, 2023). "Aside from miR-92a, two other microRNAs appear to be involved in mTOR pathway regulation in endometriosis." (PMID 37627318, 2023). "In this review, we discuss the role of the mTOR pathway in the establishment and malignant progression of endometriosis, with a focus on its interplay with other molecular pathways involved in EAOC development." (PMID 37627318, 2023). "Beclin-1 can additionally block mTOR signaling, thereby promoting apoptosis and autophagy and suppressing endometriosis in mice." (PMID 35845410, 2022). "In fact, mTOR overactivity is apparent in adenomyosis, endometriosis, and typical endometrial hyperplasia, where it promotes endometrial cell proliferation and invasiveness." (PMID 35408777, 2022). "The frequent activation of the PI3K/AKT/mTOR pathway in endometriosis makes it an attractive therapeutic target in this disease." (PMID 35408777, 2022). "The PI3K/Akt/mTOR pathway has already been reported by other researchers in endometriosis and in cancer due to its involvement with mechanisms responsible for tumor progression." (PMID 36232817, 2022). "We identified 26 leading prioritized genes involved in the PI3K/AKT/mTOR pathway, the pathway relevant to the severity of endometriosis stages." (PMID 35401535, 2022). "Functional studies also confirmed increased invasiveness by upregulation of PI3K/AKT/mTOR signaling in endometrial stromal cells, leading to progression of endometriosis." (PMID 35052864, 2022).
endometriosis (continued). "A mouse model with human endometriosis features was established and treated with three different drugs that can block ribosome biogenesis, including inhibitors against mTOR/PI3K (GSK2126458) and RNA polymerase I (CX5461 and BMH21)." (PMID 35052864, 2022). "To this end, we treated endometriosis mice with mTOR/PI3K inhibitor (GSK2126458) and RNA polymerase I inhibitors (CX5461 and BMH21) to shut down the upstream signaling for protein biosynthesis and subsequent rDNA transcription, respectively." (PMID 35052864, 2022). "During endometriosis development, the mTOR/PI3K inhibitor GSK2126458 (75 μg in 100 μL/mouse/day) and RNA polymerase-I inhibitors, CX5461 and BMH-21 (1.25 mg in 100 μL/mouse/day), were administered orally five days per week for three weeks." (PMID 35052864, 2022). "The purpose of this review is to illuminate the involvement of mTOR signaling in the pathogenesis of adenomyosis, endometriosis, endometritis, and typical endometrial hyperplasia and to address its potential as a therapeutic target for these conditions." (PMID 35408777, 2022). "Recent data show aberrant expression of various components of the mTOR pathway in both eutopic and ectopic endometrium of patients with adenomyosis or endometriosis and in hyperplastic endometrium as well." (PMID 35408777, 2022). "The ARID1A, PI3K/AKT/mTOR, MET, and HNF-1β pathways are frequently activated and are considered promising targets for the treatment of endometriosis-associated OCCC." (PMID 34659566, 2021). "Ectopic endometrial cells are found to exhibit a hyperproliferative phenotype through ROS-related activation of the MAPK/ERK and PI3K/mTOR/AKT pathways in endometriosis." (PMID 34931128, 2021). "Our functional enrichment analyses reveal some genetically controlled biological pathways underlying endometriosis and migraine including interleukin-1 receptor binding, focal adhesion-PI3K-Akt-mTOR-signaling, MAPK and TNF alpha signalling." (PMID 32121467, 2020). "The ectopic endometrium of patients with endometriosis exhibits increased phosphorylation of mTOR compared to that in the eutopic endometrium." (PMID 31649622, 2019). "Existing evidence has highlighted functionality of the PI3K/Akt/mTOR signaling pathway as a modulator of proliferation, which aids in the survival of endometriosis cells." (PMID 31262977, 2019). "The in silico analysis highlighted the ability of EPHA3 to suppress endometriosis via regulation of the mTOR signaling pathway." (PMID 31262977, 2019). "Compared to the cyclical activity of mTOR in eutopic endometrium, mTOR in endometriosis is constantly activated with persistent inhibition of cell autophagy and apoptosis." (PMID 31717614, 2019). "The present study showcased functionality of the EPHA3 as the suppressor of endometriosis via its disruption in autophagy and apoptosis of macrophages through inhibition of the mTOR signaling pathway." (PMID 31262977, 2019). "This evidence has flagged the functionality of the PI3K/AKT/mTOR pathway with a significant role in the pathogenesis of endometriosis." (PMID 31262977, 2019). "Ginsenoside Rg3 inhibits angiogenesis in a rat model of endometriosis through the VEGFR-2-mediated PI3K/Akt/mTOR signaling pathway." (PMID 30116194, 2018). "Moreover, the implication of the mTOR signaling pathway in the malignant transformation of endometriosis suggests potential therapeutic targets." (PMID 40364006, 2025). "mTOR-mediated suppression of autophagy plays a direct role in the pathogenesis of endometriosis." (PMID 41394131, 2025). "Likewise, Tanshinone IIA has been reported to alleviate osteoclastogenesis in ovariectomized mice by dampening NF‐kB and AKT signaling pathways, and also to inhibit PI3K/AKT/mTOR signaling in endometriosis by modulating angiogenesis, invasion, and adhesion." (PMID 40966112, 2025).
endometriosis (continued). "However, in endometriosis, excessive estrogen and hyperactivation of mTOR inhibit AMPK function, thereby suppressing autophagy and promoting the survival of ectopic cells." (PMID 41009686, 2025). "Interventions targeting HIF-1α and mTOR pathways may emerge as potential therapeutic targets for endometriosis." (PMID 40144566, 2025). "In our study, elevated intracellular mTOR/AKT expression in TAMs from endometriosis patients may reflect a proangiogenic phenotype, consistent with the presence of M2d-like macrophages." (PMID 40723209, 2025). "Similarly, statins, ginsenosides, and flavonoids have been reported as potential treatment candidates for endometriosis via inhibition of the mTOR pathway." (PMID 39579091, 2024). "mTOR inhibitors may be potential therapeutic agents for endometriosis as they inhibit cell proliferation, improve resistance to hormone therapy, and provide immunosuppression." (PMID 39579091, 2024). "A further evaluation of mTOR pathway inhibitors in both endometriosis and EAOC is necessary." (PMID 38893278, 2024). "In conclusion, while mTOR inhibitors, which allow for pregnancy during oral administration, show potential for clinical use in all stages of endometriosis, current evidence is limited to preclinical studies, and further research is needed to confirm clinical effectiveness." (PMID 39579091, 2024). "Preclinical studies suggest that the dosage of mTOR inhibitors needed for treating endometriosis may be lower than that required for anticancer or immunosuppressive therapy, potentially reducing dosage-dependent side effects." (PMID 39579091, 2024). "mTOR inhibitors may be potential therapeutic agents for endometriosis because of their immunosuppressive properties." (PMID 39579091, 2024). "Finally, we summarize the current advancements in mTOR-targeted therapeutics for endometriosis and EAOCs." (PMID 38893278, 2024). "Although rapamycin can provide a therapeutic treatment for endometriosis, its efficacy may be limited because of toxicity, side effects, and a ubiquitous expression of mTOR." (PMID 38645639, 2024). "Thus, autophagy induction via mTOR inhibition is emerging as a promising therapeutic strategy for endometriosis." (PMID 38645639, 2024). "In a rat model of endometriosis, the expression of mTOR was increased, and the expression of Beclin1, Bnip3, Ambra1, LC3II, and Parkin was decreased, suggesting that the autophagy level is decreased in ectopic endometrium compared to eutopic endometrium and normal endometrium." (PMID 38645639, 2024). "mTOR activation influences the development and progression of endometriosis by regulating autophagy and apoptosis factors, modulating adhesion and cell–cell adhesion molecules, promoting epithelial–mesenchymal transition angiogenesis, and controlling the microenvironment." (PMID 39579091, 2024). "Despite the growing interest in the PI3K/Akt/mTOR signalling pathway in endometriosis, there is still a significant gap in understanding the role and toxicity management of mTOR inhibitors, the only class of PI3K/Akt/mTOR pathway inhibitors with a long history of clinical use." (PMID 39579091, 2024). "Activation of the mTOR pathway may be involved in the onset or progression of endometriosis through distinct mechanisms." (PMID 39579091, 2024). "Characteristics of hormonal treatments for endometriosis and potential benefits of mTOR inhibitors." (PMID 39579091, 2024). "In fact, dienogest, which is a progestin drug approved for endometriosis treatment, works by downregulating mTOR signaling, and specifically by repressing the activity of ERK1/2 and AKT, thereby promoting apoptosis and autophagy in human endometriotic cyst stromal cells." (PMID 37627318, 2023). "Importantly, these findings concerned patients at a minimal to mild stage of endometriosis, proposing that mTOR signaling activation has a key role in the initiation of the disease, by triggering the development of ectopic lesions." (PMID 37627318, 2023).